LGR5 (leucine rich repeat containing G protein-coupled receptor 5)
Diseases named in the same sentence as LGR5 in open-access papers (continued):
Sharing a sentence is not in itself a finding about the gene and the disease.
gastric cancer (continued). "The association of LGR5 expression and patient prognosis in poorly differentiated gastric cancer may be applicable to the development of LGR5 targeted therapy and prognostic markers, but further study is desired." (PMID 33676447, 2021). "Subsequently, 2,4-diamino-quinazoline (2,4-DAQ), a selective inhibitor of Lef1, was identified to suppress the expression of Wnt/β-catenin target genes such as AXIN2, MYC and LGR5 and result in the suppression of gastric cancer cell growth through the apoptotic pathway." (PMID 32824603, 2020). "Prostaglandin D2 (PGD2) synthase (PTGDS) and its receptor PTGDR2 are negatively correlated with stem genes (Sall4 and Lgr5) in gastric cancer, which restricts tumor self-renewal, growth, and metastasis by relying on the PTGDR2 pathway to inhibit STAT3 phosphorylation and nuclear expression." (PMID 33312950, 2020). "High Lgr5/LGR5 expression is speculated to be a retained phenotype that may be reflecting the cellular origin in a subset of gastric carcinomas." (PMID 32894084, 2020). "High Lgr5 expression via TGF-β confer poor prognosis in gastric cancer." (PMID 31417548, 2019). "Our results reveal that LGR5 is a positive regulator of cell proliferation, motility, and invasion which are attributed to its indispensible role in regulating cytoskeletal reorganization and Wnt responses in gastric cancer cells." (PMID 30089773, 2018). "Our previous study indicated that LGR5 expression was correlated with gastric cancer progression." (PMID 30089773, 2018). "In addition, we found that LGR5 increased the number of pseudopodia (lamellipodia and filopodia) of gastric cancer cells, which resulted in an increasing cell motility, thereby promoting cell invasion and migration." (PMID 30089773, 2018). "A diffuse and intense cytoplasmic staining pattern for Lgr5 was detected in gastric cancer tissue." (PMID 28404940, 2017). "Our results indicate that Lgr5-specific siRNA could be developed as an effective therapeutic agent for patients with Lgr5 overexpressing gastric cancer." (PMID 28404940, 2017). "Therefore, we considered that Lgr5 participated in gastric cancer angiogenesis by enhancing Wnt/β-catenin signaling." (PMID 28404940, 2017). "Thus further in vivo studies are required to better assess the effectiveness of Lgr5-specific siRNA in inhibiting angiogenesis of gastric cancer." (PMID 28404940, 2017). "In this study, we aim to investigate the role of Lgr5 on gastric cancer angiogenesis." (PMID 28404940, 2017). "In conclusion, our results show that Lgr5 is commonly upregulated in human gastric cancer." (PMID 28404940, 2017). "Lgr5-specific siRNA could be designed into an effective therapeutic agent to inhibit gastric cancer angiogenesis." (PMID 28404940, 2017). "Silencing the expression of Lgr5 could efficiently inhibit the angiogenesis of gastric cancer at least partially through its suppression effects on VEGF expression." (PMID 28404940, 2017). "The fact that LGR5-overexpressing cells show high resistance to L-OHP at various concentrations strongly argues that CSCs and EMT are intimately associated with drug resistance in gastric cancer cells." (PMID 28033430, 2016). "It suggests that a drug targeting the LGR5-expressing tumor cells, i.e., the CSCs, could be an ideal way to treat gastric cancer or prevent relapse and metastasis." (PMID 28033430, 2016). "Tumors arise from Lgr5-expressing stem cells in the gastric antrum, undergo rapid malignant progression, exhibit foci of EMT, and activate multiple pathways previously linked to human gastric cancer." (PMID 26859571, 2016). "Furthermore, our findings suggest LGR5+ cells are a promising target to reverse IM, and potentially prevent their progression into gastric cancers." (PMID 25996368, 2015). "In addition, recent reports indicate CD44, ADAM17 and another putative stem cell marker, Musashi-1 coexpresses with stem cell markers Lgr5 in both normal and gastric cancer patient tissues." (PMID 23217022, 2012).
gastric cancer (continued). "However, in intestinal type gastric cancer the localization and number of LGR5+ cells was strikingly changed." (PMID 22530031, 2012). "Double immunostaining experiment reveals that Musashi-1 coexpresses with stem cell markers Lgr5 cell in both normal and gastric cancer patient tissues, implicating it has a role in regulating normal epithelial cell differentiation, and possibly carcinogenic processes." (PMID 23217022, 2012). "Assessment of LGR5 expression in whole mount tissue sections of intestinal type gastric carcinomas." (PMID 22530031, 2012). "In gastric cancer, the interplay between gastric cancer cells and mesenchymal stem cells sustains the growth and properties of gastric CSCs in vivo, activating the R-spondin/Lgr5 axis and the WNT/β-catenin signalling pathway, as indicated by nuclear β-catenin localisation." (PMID 38136392, 2023). "Moreover, in gastrointestinal cancers, CSCs are mostly positive for LGR5, because LGR5+ cells could produce gastric cancers." (PMID 34488885, 2021). "Furthermore, Lgr5 also plays important roles in tumorigenesis and aggression and could be useful for the evaluation of clinical outcome of gastric cancer patients." (PMID 28404940, 2017). "To clarify whether there was a relationship between the expression of IL-17RB and stemness in gastric cancer tissues, we first detected the expression of Oct4, Nanog, Lgr5, and Sall4 mRNA using real-time quantitative PCR, and analyzed the relationship between them and IL-17RB mRNA." (PMID 27146881, 2016). "Our data also showed that there was a positive correlation between IL-17RB and Oct4, Nanog, Lgr5, or Sall4 mRNA expression, and that the expression of Oct4, Sox2, and Sall4 proteins increased in proportion to the increased expression of IL-17RB in gastric cancer tissues." (PMID 27146881, 2016). "In addition, Lgr5 marked cancer cells can proliferate towards various directions inside the mucosa, indicating an invasive growth property and imply that they are crucial for gastric cancer development and progression." (PMID 23217022, 2012). "LGR5 was co-expressed with EMT markers (E-cadherin and β-catenin) and EMT inducers (PRRX1, TWIST1, and BMI1) in gastric cancer spheroids." (PMID 39821694, 2025). "LGR5 was positively correlated with distant metastasis and poor clinical outcome in CRC and gastric cancer." (PMID 39821694, 2025). "Gastric cancer stemness can be determined by investigating the expression of cell surface markers, namely CD24, CD44, and LGR5, and stemness-related transcriptional factors, namely Nanog and SOX2." (PMID 35740372, 2022). "AQP5 was significantly upregulated in CSCs isolated from gastric cancer patients and in spheroid cells, and AQP5 was coexpressed with the canonical stem marker LGR5." (PMID 36372898, 2022). "Knockdown of GRP78 expression or inhibition of GRP78 by ISL downregulated CD24, CD44, LGR5, SOX2, and Nanog in gastric cancer in our study." (PMID 35740372, 2022). "Thus, we hypothesized that the AQP5 + /LGR5 + stem cell bank is the origin of gastric cancer." (PMID 36372898, 2022). "A study by Choi and colleagues showed that theinteraction between LGR5 and FOXO1 genes play an important role in the development of gastric cancer." (PMID 33718760, 2021). "The relevance of these in vitro results to human gastric cancer is supported by the positive correlation between IL-17RB and OCT4, NANOG, LGR5, and SALL4 mRNA expression in human gastric cancer tissues." (PMID 32373132, 2020). "Among downregulated DEGs in Ubc9+/− Lgr5-EGFP+ cells, up to 17% were genes found to be repressed in early gastric cancer, colorectal adenocarcinoma, E2F1-overexpressing hepatocellular carcinoma and a subtype of basal breast cancer." (PMID 32948837, 2020). "In order to examine the role of TGF-β1 in gastric cancer, SGC-7901 cells were exposed to various concentrations of exogenous TGF-β1 ranging from 5 to 30 ng/mL for 36 h, and Lgr5 expression was shown to be concentration-dependent." (PMID 31417548, 2019).
gastric cancer (continued). "In this study, we tested the hypothesis that the response to neoadjuvant/perioperative chemotherapy correlates with the expression of four different putative cancer stem cell markers of gastric cancer (GC), i.e., LGR5, FZD7, TROY, and MIST1." (PMID 31827644, 2019). "To visualize the localization of NANOGP8 and Lgr5 in gastric cancer sphere-forming cells and adherent cells, we performed immunofluorescence double staining with NANOGP8 and Lgr5 specific monoclonal antibodies." (PMID 29689047, 2018). "There was a positive correlation between Lgr5 and VEGF expression in gastric cancer (P<0.001, r=0.305)." (PMID 28404940, 2017). "Therefore, our study suggests that Lgr5-specific siRNA could be designed into an effective therapeutic agent to inhibit angiogenesis to achieve the purpose of controlling the growth and metastasis of gastric cancer." (PMID 28404940, 2017). "The relative expression of Lgr5 and VEGF protein in cancer was significantly enhanced in gastric cancer tissue (all P=0.001) compared with normal mucosal tissue." (PMID 28404940, 2017). "To evaluate the expression level of Lgr5 and VEGF protein, we performed western blot for Lgr5 and VEGF in 75 paired gastric cancer tissues." (PMID 28404940, 2017). "Western blotting and real-time quantitative PCR (qRT-PCR) were performed to detect the expression of Lgr5 and VEGF protein and mRNA in Lgr5 siRNA-transfected gastric cancer cells." (PMID 28404940, 2017). "In present study, we first investigated the relationship between the expression of Lgr5 and VEGF and MVD status in gastric cancer tissue." (PMID 28404940, 2017). "There was a positive correlation between Lgr5 and VEGF protein in gastric cancer (r=0.921, P=0.001)." (PMID 28404940, 2017). "GCSCs were defined as Lgr5+/CD326+/CD45− cells and 1.08±0.42% GCSCs were detected in gastric cancer." (PMID 25789052, 2015). "In conclusion, we provide evidence for an increase of LGR5+ putative stem cells during gastric tumourigenesis and that the reallocation of stem cells, e.g. towards the tumour centre and invasion front, may play a role in the development and progression of gastric cancer." (PMID 22530031, 2012). "The specificity of LGR5-immunolabelling was further validated using formalin-fixed and paraffin-embedded MKN45 gastric cancer cells." (PMID 22530031, 2012). "In addition, CPT1C promotes gastric cancer drug resistance by enhancing FAO and subsequently upregulating the mRNA expression levels of gastric cancer stem cell markers (CD44, EpCam, and Lgr5)." (PMID 41219902, 2025). "Furthermore, the negative correlation of PTGDR2 with mRNA expression of OCT4, NANOG, LGR5, and SALL4 in cancerous tissues also demonstrated the relevance of these in vitro results to gastric cancer." (PMID 38704736, 2024). "Furthermore, drug resistance is substantially correlated with the expression of LGR5 and EMT-related genes in gastric cancer sphere cells." (PMID 37773114, 2023). "In our previous studies that investigated LGR5 expression in carcinomas of the stomach, colorectum, and breast, we observed no LGR5 expression in cancer-associated fibroblasts (CAFs) even in cases accompanied by extensive stromal reactions." (PMID 35778589, 2022). "Therefore, we investigated the clinicopathological relationship between LGR5 marker expression and prognosis in stage II/III gastric cancer patients." (PMID 33676447, 2021). "High LGR5 expression and EMT were reported to be correlated in gastric cancer." (PMID 33676447, 2021). "One RNAscope-based study did not uncover any difference in the OS of gastric cancer patients with varying expression of LGR5." (PMID 33676447, 2021). "Beside the Lgr5(+)/LGR5-expressing cells, more primitive MSC/MSC-like cells appear to be playing a crucial role in intestinal homeostasis, and MSC-like cells have been isolated from human gastric cancer tissues, marked by high expression of THY1." (PMID 32894084, 2020).
gastric cancer (continued). "While in gastric carcinoma, a high LGR5 expression correlated with lymphatic invasion but not with the risk of regional lymph node metastasis." (PMID 30770730, 2019). "To explore the effects of Lgr5+ cells on tumor development in the human stomach, we constructed tissue microarrays and examined the expression of LGR5 in gastric tumors obtained by ESD, including GAs and early gastric carcinomas (EGCs)." (PMID 24340024, 2013). "Using serial sections obtained from a sleeve resection specimen, which is usually obtained for the treatment of overweight, and showed no histological evidence of gastric cancer or chronic gastritis, we searched for LGR5+ epithelial cells." (PMID 22530031, 2012). "Collectively, we observed an increase in the number and intensity of LGR5+ cells from non-neoplastic epithelia to gastric cancer supporting our Real-time RT-PCR and immunohistochemistry data of matched (non-neoplastic versus neoplastic) patient cases." (PMID 22530031, 2012). "While a gradient of LGR5 expression was hardly detectable in non-neoplastic mucosa, gastric cancer frequently showed a gradient of LGR5 expression." (PMID 22530031, 2012). "Our hitherto unreported finding in gastric carcinoma indicates that especially TMA are not applicable to study the tumour biological significance of LGR5." (PMID 22530031, 2012). "Lgr5 marks cancer stem cells that give rise to both corpus and antrum/pyloric gastric cancer in mice, recapitulating the dominant gastric sites at which human non-cardia gastric cancer arises." (PMID 39191487, 2024). "Similarly, expression of common gastric cancer stem cell markers, Lgr5, and DCLK1, was more expressed in early gastric cancer than in advanced gastric cancer, and these stem cell markers involved in cancer development and progression are involved in the early stage of gastric cancer development." (PMID 34414959, 2021). "Additionally, the expression of CSC markers in poorly differentiated gastric cancer, especially LGR5, has not been reported." (PMID 33676447, 2021). "In gastric cancer, the enhanced miR-132 expression correlated chemo-resistance in GC patients, and miR-132 promoted CDDP resistance in Lgr5+ GCSCs in vitro and in vivo." (PMID 31906769, 2020). "Lgr5 has also been postulated to be a marker for cancer stem cells (CSCs) in gastric cancer, although the hypothesis is currently lacking in definitive experimental results." (PMID 32894084, 2020). "Moreover, gastric cancer patients with Lgr5+ tumors but without metastases at surgery were found to have a higher rate of recurrence or metastasis compared to patients with Lgr5− gastric tumors." (PMID 31248166, 2019). "Interestingly, Lgr5 and CD44 are two known stem cell markers, suggesting that CCAR1 may also be important for the maintenance of gastric cancer stem cells." (PMID 28230774, 2017). "The human gastric cancer cell lines MKN74, known to posses a moderate LGR5-mRNA expression (data not shown) and human non-neoplastic stomach, exhibiting very low LGR5 expression were chosen to characterize the reactivity and specificity of the anti-LGR5-antibody on protein level." (PMID 22530031, 2012). "The stemness genes (c-Myc, LGR5, ALDH1, and Nanog) were significantly upregulated in the potential gastric cancer stem cells compared with gastric cancer non-stem-like cells." (PMID 34628473, 2021).
colitis (66 papers, 2015 to 2026). Inflammation of the colon. "Lgr5+ stem cells are critical factors for maintaining cellular turnover and tissue homeostasis; however, colitis induces a loss of these cells, leading to the disruption of crypt structure." (PMID 39595338, 2024). "We then investigated the effectiveness of conditionally ablating PKM2 in Lgr5+ intestinal stem cells (ISC) using a mouse model of colitis-associated CRC (AOM plus DSS)." (PMID 30996297, 2019). "An Lgr5+-independent population of stem cells maintains homeostasis in the colon and is associated with colitis-associated regeneration." (PMID 31708126, 2019). "Loss of Mettl3 in IECs or Lgr5+ stem cells suppressed the differentiation and self-renewal of ISCs, especially restricted the early differentiation and maturation of goblet cells in colon, and then induced colitis." (PMID 39762134, 2025). "Thus, a multitude of effects on gut microbiome, differential gene expression, and/or expansion of Lgr5(+) stem cells seem to underlie amelioration of colitis following dietary intervention." (PMID 35008767, 2021). "Importantly, loss of Lgr5+ ISCs happened at the early stage of colitis." (PMID 39949764, 2025). "Notoginsenoside R1 can reduce heart damage caused by high altitude hypoxia in rats by activating ERK1/2, in addition to increase Lgr5+ stem cell and epithelial healing in colitis mice by stimulating Wnt/β-Catenin signaling." (PMID 40417210, 2025). "Patients with ulcerative colitis and mice with DSS-induced colitis show a reduction in Lgr5+ cells in the small intestine, impair epithelial self-renewal, and result in intestinal dysfunction." (PMID 41316490, 2025). "Consistent with our previous report using a colitis-induced tumor model, expression of stem cell marker genes including Lgr5 was reduced in KO organoids." (PMID 38659853, 2024). "Lgr5 was highly expressed in the TZ in the early stages of colitis, followed by higher expression levels of SOX2." (PMID 39684417, 2024). "Co-treatment with Wnt inhibitor ICG-001 partially counteracted the effects of NGR1 on crypt Lgr5+ ISCs, organoid budding rates, and overall mice colitis improvement." (PMID 38491161, 2024). "Knockout models have shown that myofibroblasts are the source of stromal Rspo3, which is essential for the regeneration and differentiation of Axin2- crypt cells after destruction of Lgr5+ and Axin2+ cells following colonic inflammation." (PMID 39461590, 2024). "In this study, we demonstrated that NGR1, a natural phytoestrogen, exerts its beneficial effects on colitis by suppressing inflammation and promoting Lgr5+ stem cell and epithelial regeneration through the activation of the Wnt signaling pathway." (PMID 38491161, 2024). "This is consistent with our previous report that DKK2 enhanced Lgr5 expression in colitis-induced cancer cells via HNF4α1, an isoform of HNF4A." (PMID 38659853, 2024). "In vivo, de novo synthesized locally high 1,25(OH)2D concentrations significantly elevated local 1α-hydroxylase expression, robustly suppressed experimental colitis, and promoted Lgr5+ ISC differentiation." (PMID 39273035, 2024). "Robo1, the receptor for the secreted glycoprotein Slit2, mediates DSS-induced colitis by activating the autophagy of Lgr5+ ISCs." (PMID 38891118, 2024). "Loss of Tsc2 in the colonic epithelium suppressed WNT pathway, leading to a decrease in the number of Lgr5+ colonic stem cells and an increased susceptibility to DSS‐induced colitis." (PMID 39465140, 2024). "This is also apparent upon DSS-induced colitis where the expression of Hopx and Lgr5 remains higher in the morphologically intact proliferating crypts of Bmal1+/+ controls at 6 days but is decreased in Bmal1-/- mutant animals." (PMID 35223537, 2022).